PRL (prolactin)
Diseases named in the same sentence as PRL in open-access papers (continued):
Sharing a sentence is not in itself a finding about the gene and the disease.
Sepsis (9 papers, 2014 to 2024). Sepsis is defined as life-threatening organ dysfunction caused by a dysregulated host response to infection. "It should be noted that elevated PRL levels have been associated with improved outcomes in sepsis due to them enhancing immune function, suggesting a potential benefit in critical illnesses." (PMID 39595974, 2024). "The association of prolactin with modulation of the immune system during sepsis has been studied in septic mice, where administration of prolactin was associated with decreased survival and alterations in immune response." (PMID 25243181, 2014). "The administration of prolactin during experimental polymicrobial sepsis in mice increased the mortality rate from 47% to 81%." (PMID 32708472, 2020). "In patients with sepsis or septic shock a clear rise in PRL levels is seen in the first days after the occurrence of a stressful life-threatening event." (PMID 31340197, 2019). "Except for CRH, septic patients have increased ACTH, growth hormone, and prolactin levels in the early stage of sepsis." (PMID 25243181, 2014). "The decrease in PIP found in our study could be related to a decrease in prolactin, which has been described in pigs with inflammation and humans with sepsis." (PMID 37092455, 2023). "Sepsis is a condition of complex physiological changes, and to ensure areliable diagnosis, other laboratory criteria should be evaluated, such as bloodculture, inflammatory markers, such as C-reactive protein or prolactin, whenfeasible." (PMID 30916236, 2019). "Although pharmacological blockade of prolactin might offer an innovative therapeutic intervention, the exact role of prolactin and its relation to hGRα in sepsis have still to be delineated." (PMID 28224564, 2017). "The increased prolactin concentrations in our septic patients, have been previously shown to inhibit cellular immune functions in septic mice, decreasing survival, and to play a role in the acute stress response in sepsis." (PMID 28224564, 2017). "Our findings of significantly increased ACTH, cortisol, and prolactin levels in severe sepsis and septic shock also support the hypothesis that prolactin, apart from cortisol, may have a role in the acute stress hormonal response in the early-onset inflammatory process." (PMID 25243181, 2014). "Furthermore, prolactin administration profoundly affected cellular cytokine release (IL-2, IL-6, IFN-γ) 48 h after induction of sepsis by cecal ligation and puncture." (PMID 32708472, 2020). "The role of prolactin as an early acute stress in adult ICU sepsis and trauma patients has not been elucidated yet." (PMID 25243181, 2014). "Thus, our study demonstrated that stress response of prolactin and its relation to the severity of sepsis might not have been induced through the iHSP72 or iHSP90α “danger signal” pathways." (PMID 25243181, 2014).
alcoholism (8 papers, 2010 to 2025). "In contrast, unique pathways identified from M-AD switch genes associated with alcoholism, nicotine addiction, cell adhesion molecules, prolactin signaling, adipocytokine signaling, and oxytocin signaling." (PMID 36389068, 2022). "In contrast, nicotine addiction, cell adhesion molecules, oxytocin signaling, adipocytokine signaling, prolactin signaling, and alcoholism are uniquely associated with M-AD." (PMID 36389068, 2022). "In contrast to females, the unique pathways associated with switch genes in M-AD were oxytocin and prolactin signaling, cell adhesion molecules, alcoholism, adipocytokine signaling, and nicotine addiction." (PMID 36389068, 2022).
benign prostatic hyperplasia (8 papers, 2006 to 2024). A non-cancerous nodular enlargement of the prostate gland. "Pb-PRL mice have been shown to develop prostatic hyperplasia with associated interstitial inflammation." (PMID 35440548, 2022). "Based on studies in rodents, the involvement of PRL in benign prostate diseases [benign prostate hyperplasia (BPH), inflammation] has also been suggested, but there are currently no data on its role in the pathogenesis of these conditions in humans." (PMID 38370355, 2024). "According to former reports involving Pb-PRL mice, this study confirmed that prostate hypertrophy was detectable from 3 months of age in Pb-PRLSTAT5f/f mice compared to control mice." (PMID 31269779, 2019). "Our suggestion then, is that this minute elevation of PRL could be at the etiology of prostate hyperplasia and/or cancer." (PMID 16707016, 2006). "Serum concentrations of prolactin (PRL), insulin‐like growth factor‐1 (IGF‐1) and 25 hydroxyvitamin D3 (25‐OHD3) were analysed to investigate their possible involvement in the pathogenesis of benign prostatic hyperplasia (BPH)." (PMID 34015193, 2021).
bladder cancer (8 papers, 2020 to 2025). "We showed that the first five significant pathways of B7-H4 were enriched: arginine biosynthesis, bladder cancer, phototransduction, prolactin signaling pathway, and proximal tubule bicarbonate reclamation." (PMID 38850312, 2024). "The results showed that bladder cancer (hsa:05219), platinum drug resistance (hsa:01524), prolactin signaling pathway (hsa:04917), small cell lung cancer (hsa:05222), IL-17 signaling pathway (hsa:04657), and TNF signaling pathway (hsa:04668) were highly enriched." (PMID 37759722, 2023).
Chagas disease (8 papers, 2013 to 2025). A parasitic infection caused by Trypanosoma cruzi. ": hsa04350: TGF-beta signalling pathway, hsa04068: FoxO signalling pathway, hsa05142: Chagas disease (American trypanosomiasis), hsa04380: Osteoclast differentiation, hsa04520: Adherens junction and hsa04917: Prolactin signalling pathway." (PMID 35840955, 2022). "In Chagas disease, glucocorticoids induce thymic atrophy, which can be countered by dehydroepiandrosterone and prolactin." (PMID 34113341, 2021). "Although pro-inflammatory cytokines released during infection have been identified as potentstimulators of GC synthesis by the adrenal gland, nothing is known on the role of PRL upon the systemic GC rise seen inexperimental Chagas disease." (PMID 24324845, 2013). "Thus, prolactin is a vital immune mediator and a potential area for immunotherapy development for Chagas disease." (PMID 39781597, 2025).
diabetic retinopathy (8 papers, 2014 to 2026). "Overexpression of PRL in patients with diabetic retinopathy results in accumulation of vasoinhibins in the retina, inhibition of vascular endothelial growth factor (VEGF), inactivation of nitric oxide synthase (NOS), and prevention of retinal vasopermeability." (PMID 36078009, 2022). "Landmark original research articles and reviews highlighting the involvement of the prolactin/vasoinhibin axis in diabetic retinopathy." (PMID 36157442, 2022). "Prolactin’s role in light-induced retinal degeneration and in diabetic retinopathy has been investigated for nearly four decades." (PMID 33432105, 2021). "Circulating PRL influences the progression of diabetic retinopathy after its intraocular conversion to vasoinhibins." (PMID 25431591, 2014). "• These findings may encourage future research to explore the potential role of prolactin-elevating antidopaminergic agents in diabetic retinopathy." (PMID 41758375, 2026). "Therefore, PRL could be explored as a therapeutic agent for patients with diabetic retinopathy or any other disease that involves an alteration in ocular angiogenesis." (PMID 36078009, 2022).
glioblastoma (8 papers, 2013 to 2023). The most malignant astrocytic tumor (WHO grade IV). "Ducret and colleagues demonstrated increased intracellular calcium in glioblastoma cells induced by the presence of PRL, increased thymidine incorporation, cell growth and half-life." (PMID 23317095, 2013). "We therefore speculate that HCMV is a driving force for disease progression of glioblastoma via many different pathways including the PRL/PRLR axis." (PMID 32121009, 2020). "Although prolactin (PRL) and its receptor (PRLR) have been detected in glioblastoma multiforme (GBM), their role in its pathogenesis remains unclear." (PMID 31862900, 2019).
hepatocellular carcinoma (8 papers, 2013 to 2022). A malignant tumor that arises from hepatocytes. "It was reported that 8 to 68% of 44 patients with hepatocellular carcinoma had increased levels of α- and β-human chorionic gonadotropin (hCG) subunits, calcitonin, parathyroid hormone (PTH), prolactin (PRL), adrenocorticotropic hormone (ACTH) and growth hormone (GH)." (PMID 24137355, 2013).
invasive breast carcinoma (8 papers, 2007 to 2025). A carcinoma that infiltrates the breast parenchyma. "Another association was observed between invasive breast cancer risk in postmenopausal women with high circulating PRL, particularly for ER-positive disease." (PMID 40160874, 2025). "An association is observed between invasive breast cancer risk in postmenopausal women with high circulating PRL, particularly for ER-positive disease." (PMID 36187116, 2022). "Previous studies suggest that high PRL levels can increase the risk of invasive breast cancer in women." (PMID 34651424, 2021). "Increased circulating levels of prolactin have been associated with increased risk of both in situ and invasive breast cancer." (PMID 28717404, 2017). "Our findings of modest, positive associations between prolactin and in situ breast cancer risk are similar to those observed for invasive breast cancer." (PMID 25887963, 2015). "The relationship between circulating prolactin and invasive breast cancer risk has been investigated previously." (PMID 25887963, 2015). "In our previous study we found a modest positive association between circulating prolactin levels and invasive breast cancer risk among postmenopausal women (odds ratio (OR)Q4-Q1 = 1.29 (95% CI 1.05,1.58), Ptrend = 0.09)." (PMID 25887963, 2015). "Prior analyses limited to invasive cases found modest significant associations between circulating prolactin and risk of invasive breast cancer, with up to a 50% increase in risk contrasting top versus bottom quartiles." (PMID 25887963, 2015). "The relationship between circulating prolactin and invasive breast cancer has been investigated previously, but the association between prolactin levels and in situ breast cancer risk has received less attention." (PMID 25887963, 2015). "In conclusion, we have extended prior research showing an association between prolactin and invasive breast cancer to the outcome of in situ breast cancer." (PMID 25887963, 2015). "We then determined whether the PRL-upregulated gene signature was associated with clinical outcome, using an available 49 of 75 PRL-upregulated genes in a cohort of 936 primary invasive breast cancer patients." (PMID 23758962, 2013). "In invasive breast cancer, there is a shift in PRL signaling from STAT5-mediated pathways to focal-adhesion kinase and MAPK pathways, thereby favoring proliferation." (PMID 36187116, 2022). "Our data extends prior research linking prolactin and invasive breast cancer to the outcome of in situ breast tumours and shows that higher circulating prolactin is associated with increased risk of in situ breast cancer." (PMID 25887963, 2015). "Prolactin may also play a role in progression from in situ to invasive breast cancer." (PMID 25887963, 2015).
malaria (8 papers, 2018 to 2025). Malaria is a serious and sometimes fatal disease caused by a parasite that commonly infects a certain type of mosquito which feeds on humans. "Although several studies reported the association between cortisol and prolactin levels with malaria in pregnancy, very few studies have investigated the evolution of cortisol and prolactin concentrations according to the stage and age of gestation." (PMID 39495748, 2024). "We conducted a study in pregnant women living in a malaria endemic area to determine the potential effect of gestational age on the modulation of the endocrine system by cortisol and prolactin production during pregnancy." (PMID 39495748, 2024). "The present study was designed to investigate the potential effect of gestation in modulating cortisol and prolactin levels in peripheral blood samples during pregnancy and in cord blood at delivery in a malaria endemic area." (PMID 39495748, 2024). "Lower prolactin levels in infected females suggest it plays a role in malaria, particularly in placental malaria." (PMID 39492784, 2024). "Nevertheless, the psychological impact of the first pregnancy could partly explain the higher production of cortisol and prolactin in primigravida compared to multigravida as well as the higher prevalence of malaria at enrolment." (PMID 39495748, 2024). "However, some argue that increased cortisol, not prolactin, reduces NK cytotoxicity and heightens malaria risk in pregnant women." (PMID 39492784, 2024).
mastalgia (8 papers, 2019 to 2025). "Increased PRL levels have been linked with mastalgia and some symptoms of PMS." (PMID 38075075, 2023). "Observation indicated that excessive soy food consumption would increase the serum levels of prolactin, progesterone and estrogen and prolong the duration of cyclical mastalgia." (PMID 41488812, 2025). "Bromocriptine, a dopamine agonist, effectively inhibits the synthesis and secretion of prolactin from the hypothalamus, with an effective rate of 54% for cyclical mastalgia." (PMID 41488812, 2025). "Three months Vitex therapy can decrease prolactin level in women with complaints of cyclic mastalgia (Dinç and Coşkun, 2014)." (PMID 37655000, 2023). "Additionally, after the cyclic mastalgia subsided, prolactin required a longer time than estradiol to return to the lower level." (PMID 41488812, 2025). "The clinical pharmacological effects of VAC extract are not clear, yet, but supposed to be due to a dopaminergic activity in the hypothalamic-pituitary–gonadal axis, leading to reduced prolactin secretion and potentially alleviating symptoms of PMS and associated mastalgia/mastodynia." (PMID 38393671, 2024). "The reduction of PRL after VAC administration has been demonstrated elsewhere, including a decrease in TRH-stimulated PRL release and among women with mastalgia." (PMID 38075075, 2023). "As for mastalgia, the condition is largely hormonally mediated, primarily influenced by cyclical fluctuations in estrogen and prolactin levels rather than inflammatory pathways." (PMID 41267881, 2025). "Previous studies have shown the relationship between reducing serum prolactin level and ameliorating premenstrual mastalgia with bromocriptine as a synthetic dopaminergic agent and several scientific studies support the efficacy of Vitex extracts in the management of PMS and cyclical mastalgia." (PMID 32641968, 2019).
Ovarian cyst (8 papers, 2014 to 2025). The presence of one or more cysts of the ovary. "Studies have also shown that elevated PRL levels are associated with the formation of ovarian cysts in animal models, and treatment with bromocriptine—a dopamine agonist—can reduce PRL levels and inhibit cyst formation." (PMID 40150506, 2025). "Thus, it can be seen that estrogen, increased levels of progesterone, and prolactin are associated with the ovarian cyst." (PMID 33623786, 2021). "When multiple ovarian cysts occur in women of reproductive age, serum E2 and PRL levels increase, FSH levels increase or are normal, and LH levels decrease." (PMID 34248835, 2021). "Following treatment with bromocriptine, PRL levels normalized, and although the elder sister’s PRL levels increased after discontinuing the medication, ovarian cysts did not recur." (PMID 40150506, 2025).
Sheehan’s syndrome (8 papers, 2017 to 2025). "Growth hormone and prolactin deficiencies are the most common hormonal disturbances, occurring in 90-100% of Sheehan’s syndrome cases, followed by deficiencies in gonadotrophins, thyrotrophin, and corticotrophin, which occur in 50-100% of cases." (PMID 40621290, 2025). "Sheehan syndrome, and combined surgery and radiotherapy were found to be more common in PRL deficient patients." (PMID 38700812, 2024). "All of the patients who received combined surgery and radiotherapy or had Sheehan syndrome were PRL deficient." (PMID 38700812, 2024). "Elevated prolactin levels are uncommon and associated with poor prognosis in patients with Sheehan’s syndrome." (PMID 34779875, 2022). "Most conditions associated with low prolactin levels develop only (Sheehan's syndrome) or mainly (lymphocytic hypophysitis) in women, and women are treated with dopamine agonists much more often than men." (PMID 36195057, 2022). "This can be idiopathic or the result of a genetic mutation in the prolactin gene, postpartum pituitary necrosis caused by peripartum hemorrhage (Sheehan’s syndrome), or autoantibodies against lactotrophs, the prolactin-producing cells in the anterior pituitary." (PMID 40792031, 2025). "An elevated prolactin level may provide a hint that a case of Sheehan’s syndrome is severe, as it may indicate major damage with the loss of pituitary mass." (PMID 34779875, 2022). "In an analysis of patients with Sheehan syndrome, we suggested a basal cut-off level of < 4 ng/ml for hypoprolactinemia and > 7.8 ng/ml for normal PRL levels." (PMID 38700812, 2024). "Prolactin may be involved in lactotroph cell recovery in patients with Sheehan’s syndrome; one such patient was reported to lactate during a second pregnancy." (PMID 34779875, 2022). "Prolactin elevation could suggest that a case of Sheehan’s syndrome is severe." (PMID 34779875, 2022).
thyroid cancer (8 papers, 2019 to 2025). "GO and KEGG analyses revealed significant biological processes, molecular functions, cellular components, and pathways, including PPAR signaling, thyroid cancer, and prolactin pathways." (PMID 40599803, 2025). "Protein targets, ESR1 and MAP2K1, act through prolactin, thyroid cancer, endocrine resistance, GnRH secretion, and estrogen signaling pathways." (PMID 38338298, 2024).